RHO (rhodopsin)
Diseases named in the same sentence as RHO in open-access papers (continued):
Sharing a sentence is not in itself a finding about the gene and the disease.
retinitis pigmentosa (continued). "Rho−/− mice are B6 background mice developed by targeted disruption of the rhodopsin gene, which is an animal model for retinitis pigmentosa." (PMID 21750603, 2011). "We took advantage of the ability of embryonic stem cells to survive long-term in foreign tissue and used these cells to deliver neuroprotectant molecules to the retina of the rhodopsin TgN S334ter-4 rat model of retinitis pigmentosa (RP)." (PMID 19461934, 2009). "Disruption of this bond in rhodopsin leads to ER retention and retinitis pigmentosa." (PMID 40650136, 2025). "Similarly, rhodopsin is mislocalised in Rp1−/− mouse photoreceptors, mutations in RP1 cause Retinitis Pigmentosa 1, and IFT81 has been reported as candidate gene for non-syndromic retinal dystrophy." (PMID 39934925, 2025). "For instance, monitoring rhodopsin expression in photoreceptors may aid in the management of hereditary retinal degeneration (including retinitis pigmentosa) or AMD." (PMID 40002553, 2025). "In Prph2 “null” Rds mice, the lack of peripherin downregulates rhodopsin gene expression, causing a gradual loss of rod cells characteristic of macular diseases as retinitis pigmentosa." (PMID 35656327, 2022). "Rhodopsin-associated (RHO-associated) retinitis pigmentosa (RP) is a progressive retinal disease that currently has no cure." (PMID 35472194, 2022). "Other non-inhibitory ligands, which bind the active site and stabilize some mutants in the cells, have been described, 11-cis-retinal and tetrahydrobiopterin, which are the natural cofactors of rhodopsin and phenylalanine-hydroxylase respectively, for retinitis pigmentosa and phenylketonuria." (PMID 31940970, 2020). "Using a genetic model (rd10 mice) of retinitis pigmentosa, which results in progressive rod photoreceptor-specific cell death showed that EVs isolated from retinal explants contain rhodopsin protein." (PMID 32670023, 2020). "In addition to modeling the human disorder recessive retinitis pigmentosa, knockout animals will be useful for future examinations of the role of rhodopsin in regulating rod outer segment disk membrane synthesis." (PMID 28761125, 2017). "This might be a problem for the use of rhodopsin, particularly in retinitis pigmentosa patients with photoreceptor degeneration or in patients with RPE dysfunction, which is often the case with atrophic macular degeneration." (PMID 27679671, 2016). "Chemical chaperone could attenuate UPR signaling and ER stress induced by T17M rhodopsin and has potential therapeutic significance for retinitis pigmentosa." (PMID 25530840, 2014). "In addition, cytoplasmic accumulation of proteins often implicates various neurodegenerative disorders, including the accumulation of rhodopsin in retinitis pigmentosa and the accumulation of polyQ-expanded huntingtin in Huntington's disease." (PMID 23754968, 2013). "For example, in rhodopsin the non-synonymous (ns) SNP A164V4.53 destabilizes helix packing resulting in protein misfolding and causes retinitis pigmentosa, similarly the T164I4.56 nsSNP in β2-AR is hypofunctional and is associated with coronary and peripheral artery disease." (PMID 22272267, 2012). "A recent study of the rhodopsin knockout (rho−/−) mouse, a murine model of human retinitis pigmentosa, demonstrated that the migration of RPE cells along blood vessels within the inner retina is triggered by the close approximation and direct contact of the inner retinal vessels with the RPE." (PMID 22065924, 2011). "Thus, LEDGF1-326 might be a suitable therapeutic agent for reducing rhodopsin aggregates and preventing cellular degeneration in diseases like retinitis pigmentosa." (PMID 21915354, 2011). "RP1 completes the triad (RHO, PRPH2, RP1) of genes with highest prevalence for retinitis pigmentosa." (PMID 25506321, 2014). "Mutations in RHO and PDE6B, but not GNAT1, are also described in retinitis pigmentosa (RP)." (PMID 24760071, 2014).
autosomal dominant retinitis pigmentosa (94 papers, 2009 to 2026). Autosomal dominant retinitis pigmentosa (RP) is an autosomally dominant inherited retinal dystrophy leading to progressive loss of the photoreceptors and retinal pigment epithelium and resulting in blindness usually after several decades. "The majority of cases of autosomal-dominant retinitis pigmentosa (adRP) are associated with rhodopsin (RHO) variants." (PMID 41716464, 2026). "Background/Objectives: The RhoP23H/WT mouse line is a commonly used model to study rhodopsin P23H-associated autosomal dominant retinitis pigmentosa." (PMID 41562848, 2026). "One of the most common causes of autosomal dominant retinitis pigmentosa is the proline to histidine point mutation at codon 23 (P23H) in the rhodopsin gene (RHO)." (PMID 41562848, 2026). "The P23H variant of rhodopsin (RHO) is a common cause of autosomal dominant retinitis pigmentosa (adRP)." (PMID 40592891, 2025). "NDR2 kinase regulates retinal interneuron proliferation and homeostasis and its absence in the Ndr2 mouse knockout results in rhodopsin mislocalization, which is known to cause blindness in autosomal dominant retinitis pigmentosa." (PMID 39774853, 2025). "Mutations in rhodopsin are the leading cause of autosomal dominant retinitis pigmentosa (adRP), making this receptor a critical therapeutic target." (PMID 41009537, 2025). "The ciliary-targeting signal (CTS) VxPx is a hotspot for mutations that interfere with rhodopsin transport, causing severe forms of autosomal dominant retinitis pigmentosa (adRP) and blindness." (PMID 39774853, 2025). "In animal models for autosomal dominant Retinitis pigmentosa due to mutations in the RHO gene, recent preclinical findings indicate that treating imbalanced proteostasis by pharmacological inhibition of the VCP/proteasome rescues photoreceptor degeneration." (PMID 40103630, 2025). "We performed this study in the P23H rhodopsin‐mutated mouse model (P23H Rho) that mimics one major cause of human autosomal dominant retinitis pigmentosa." (PMID 40171795, 2025). "Most mutations in rhodopsin are caused by defects in proper folding or transport to the outer segment, resulting in autosomal dominant retinitis pigmentosa (RP)." (PMID 40429749, 2025). "Numerous mutations in rhodopsin promote receptor misfolding and aggregation, causing autosomal dominant retinitis pigmentosa, a progressive retinal degenerative disease." (PMID 39875362, 2025). "We assessed the potential of retinal organoids for optimizing CRISPR-Cas9-mediated gene editing, focusing on the therapeutically relevant RHO gene implicated in autosomal dominant retinitis pigmentosa (adRP)." (PMID 41376775, 2025). "Mutations in the gene encoding rhodopsin (RHO) are a common cause of autosomal dominant retinitis pigmentosa (adRP) in the United States." (PMID 40592891, 2025). "Dysfunction in rhodopsin is a leading cause of autosomal dominant retinitis pigmentosa (adRP), a progressive retinal degenerative disease currently without a cure." (PMID 39875362, 2025). "NHEJ is useful to knock-out gain-of-function or dominant-negative mutations such as Rhodopsin (Rho) gene mutations in autosomal dominant retinitis pigmentosa (ADRP)." (PMID 39064263, 2024). "Autosomal dominant retinitis pigmentosa (AD-RP) is caused by several genes, among which RHO is one of the most investigated." (PMID 39336749, 2024). "Dominant mutations in the rhodopsin gene (Rho) contribute to 25% of autosomal dominant retinitis pigmentosa (adRP), characterized by photoreceptor loss and progressive blindness." (PMID 38828393, 2024). "Mutations in the rhodopsin-encoding gene RHO are the leading cause of autosomal dominant retinitis pigmentosa (ADRP)." (PMID 37077319, 2023). "The P23H mutant rhodopsin transgenic rat is an experimental model of retinal degeneration that exhibits progressive photoreceptor loss with similar properties as human autosomal dominant retinitis pigmentosa (RP)." (PMID 36312296, 2022).
autosomal dominant retinitis pigmentosa (continued). "P23H rats express a variant of rhodopsin with a mutation that leads to loss of visual function with similar properties as human autosomal dominant retinitis pigmentosa (RP)." (PMID 36312296, 2022). "P23H transgenic pigs carry the human Pro23His rhodopsin mutation representing the most common form of human autosomal dominant retinitis pigmentosa." (PMID 35256656, 2022). "For instance, mutations in the RHO gene encoding for rhodopsin, that cause protein misfolding and aggregation, are the most common cause of autosomal dominant retinitis pigmentosa (adRP)." (PMID 35873807, 2022). "Mutations in the rhodopsin gene are the most common form of autosomal-dominant retinitis pigmentosa (adRP), and the variant RHOP23H is the most common cause of adRP in the United States." (PMID 35409251, 2022). "The P23H mutation in rhodopsin (Rho), the rod visual pigment, is the most common allele associated with autosomal-dominant retinitis pigmentosa (adRP)." (PMID 35275162, 2022). "In a recent phase I/II clinical trial, a specific ASO showed good results in treating Leber congenital amaurosis 10, Usher syndrome type 2 and (rhodopsin) RHO-associated autosomal-dominant retinitis pigmentosa." (PMID 34200613, 2021). "Rhodopsin (RHO) gene mutations are a common cause of autosomal dominant retinitis pigmentosa (ADRP)." (PMID 34400638, 2021). "In this study we examine the role α-crystallins play in protecting photoreceptor cells in a model of autosomal dominant retinitis pigmentosa caused by a mutation in the rhodopsin gene that results in the misfolding of the rhodopsin protein." (PMID 35008496, 2021). "Mutations in the G protein-coupled receptor (GPCR) rhodopsin are a common cause of autosomal dominant retinitis pigmentosa, a blinding disease." (PMID 34006992, 2021). "Rhodopsin (RHO) misfolding mutations are a common cause of the blinding disease autosomal dominant retinitis pigmentosa (adRP)." (PMID 34680161, 2021). "P23H and D190N are two common mutations in the rhodopsin (RHO) gene that result in the autosomal dominant retinitis pigmentosa (ADRP)." (PMID 33926102, 2021). "Mutations in rhodopsin are the most common cause of autosomal dominant retinitis pigmentosa (RP), a blinding disease that afflicts more than 1.5 million individuals world-wide." (PMID 34006992, 2021). "Rhodopsin (RHO) is the most well-known genetic cause of autosomal dominant retinitis pigmentosa (adRP)." (PMID 34666717, 2021). "Tvrm4 mice, a model of autosomal dominant retinitis pigmentosa (RP), carry a mutation of Rhodopsin gene that can be activated by brief exposure to very intense light." (PMID 32435178, 2020). "Mutations in the RHO (rhodopsin) gene are the most common cause of autosomal dominant retinitis pigmentosa, accounting for 20 to 30% of all cases of RP5,6." (PMID 33230161, 2020). "Rhodopsin is mislocalized to the inner segment plasma membrane (IS PM) in various blinding disorders including autosomal-dominant retinitis pigmentosa caused by class I rhodopsin mutations." (PMID 32376599, 2020). "Mutations in the gene rhodopsin are one of the major causes of autosomal dominant retinitis pigmentosa (adRP)." (PMID 33137101, 2020). "For patients with autosomal dominant retinitis pigmentosa (RP), the most frequently associated genes were RHO, RP1, and PRPF31; for X-linked and autosomal recessive forms of RP, the most frequently associated genes were RPGR and USH2A, respectively." (PMID 32423767, 2020). "Rhodopsin misfolding caused by the P23H mutation is a major cause of autosomal dominant retinitis pigmentosa (adRP)." (PMID 32196553, 2020). "Mutations in the RHO gene encoding for the visual pigment protein, rhodopsin, are among the most common cause of autosomal dominant retinitis pigmentosa (ADRP)." (PMID 31100078, 2019). "The P23H variant of rhodopsin results in misfolding of the protein, and is a common cause of the blinding disease autosomal dominant retinitis pigmentosa (adRP)." (PMID 31320609, 2019).
autosomal dominant retinitis pigmentosa (continued). "The rhodopsin P23H mutation, the most common mutation in autosomal dominant Retinitis Pigmentosa (RP), produced increased ER stress levels compared to wild type (WT) rhodopsin." (PMID 31920544, 2019). "The P23H rhodopsin mutation represents the most common mutation among autosomal dominant retinitis pigmentosa (adRP) patients in North America8." (PMID 29773803, 2018). "The binding of wild-type (WT) human arrestin-1 and several mutants with substitutions in position 147 (including C147F, which causes dominant retinitis pigmentosa in humans) to phosphorylated and unphosphorylated light-activated rhodopsin was determined." (PMID 29305604, 2018). "This conclusion supports our recent report in which we showed that certain rhodopsin mutants associated with autosomal dominant retinitis pigmentosa also reconstitute into vesicles as monomers while retaining WT-like scramblase activity." (PMID 29196630, 2017). "Mutations in rhodopsin, the light-sensitive protein of rod cells, are the most common cause of dominant retinitis pigmentosa (RP), a type of inherited blindness caused by the dysfunction and death of photoreceptor cells." (PMID 29036441, 2017). "Inherited mutations in rhodopsin (RHO), the light sensitive protein of rod photoreceptor cells, are the most common cause of autosomal dominant retinitis pigmentosa (adRP)." (PMID 28065882, 2017). "As a transcriptional repression target we selected the G-protein-coupled Receptor Rhodopsin (RHO) gene whose gain-of-function mutations are those most commonly associated with autosomal dominant retinitis pigmentosa (adRP), an incurable form of blindness." (PMID 26974343, 2016). "Mutations in rhodopsin, the light-sensitive protein of rod cells, are the most common cause of autosomal dominant retinitis pigmentosa (ADRP)." (PMID 25055872, 2014). "The P23H mutation in rhodopsin (RhoP23H) is a prevalent cause of autosomal dominant retinitis pigmentosa." (PMID 24523853, 2014). "Hsp90 inhibition activates the heat shock response and can improve viability in a cell model of the P23H misfolding mutation in rhodopsin that causes autosomal dominant retinitis pigmentosa (adRP)." (PMID 24301679, 2014). "The S334ter rhodopsin (Rho) rat (line 4) bears the rhodopsin gene with an early termination codon at residue 334 that is a model for several such mutations found in human patients with autosomal dominant retinitis pigmentosa (ADRP)." (PMID 22432009, 2012). "In this review, we examine some of the gene delivery approaches used to treat animal models of autosomal dominant retinitis pigmentosa, focusing on those models associated with mutations in the gene for rhodopsin." (PMID 23077406, 2012). "The P23H mutation in the rhodopsin gene causes rhodopsin misfolding, altered trafficking and formation of insoluble aggregates leading to photoreceptor degeneration and autosomal dominant retinitis pigmentosa (RP)." (PMID 21738619, 2011). "The most common Rhodopsin (Rh) mutation associated with autosomal dominant retinitis pigmentosa (ADRP) in North America is the substitution of proline 23 by histidine (RhP23H)." (PMID 20865169, 2010). "The P23H mutation in the rhodopsin gene was the first identified as a cause of autosomal dominant retinitis pigmentosa in humans." (PMID 20806040, 2010). "In human, rhodopsin mutations accounting for its intracellular mislocalization are the most frequent cause of autosomal dominant Retinitis Pigmentosa (RP), a degenerative retinal pathology characterized by progressive blindness." (PMID 19572012, 2009). "Over 100 mutations in the light-sensing molecule rhodopsin have been identified in patients with autosomal dominant retinitis pigmentosa." (PMID 19214218, 2009). "In human, mutations in rhodopsin involving its intracellular mislocalization, are the most frequent cause of autosomal dominant Retinitis Pigmentosa, a degenerative retinal pathology characterized by progressive blindness." (PMID 19572012, 2009).
autosomal dominant retinitis pigmentosa (continued). "Importantly, several patient mutations in the corresponding proline in rhodopsin have been identified and linked to autosomal dominant retinitis pigmentosa (adRP), including P171S, P171Q, and P171L." (PMID 38410159, 2024). "Mutant RHO is the most frequent genetic cause of autosomal dominant retinitis pigmentosa (adRP)." (PMID 37272616, 2023). "Importantly, gene augmentation therapy also has great potential to treat other inherited disorders in the retina, such as autosomal dominant retinitis pigmentosa (adRP), which can be caused by mutations in over 25 known genes including RHO and RPE6538." (PMID 31836750, 2019). "For example, mice with autosomal dominant retinitis pigmentosa due to ER retention of mutant rhodopsin have retinal damage that is associated with UPR and CHOP upregulation; however, deletion of CHOP led to increased retinal damage in these mice, suggesting a protective role for CHOP." (PMID 28325753, 2017). "Consistent with the importance of Glu-181 in rhodopsin function is the observation that human mutations in rhodopsin at this site (E181K) are associated with autosomal dominant retinitis pigmentosa and have been identified repeatedly in diverse populations (68, –, 70)." (PMID 26195627, 2015). "Interestingly, formation of toxic Rhodopsin-Arrestin complexes is also reported for mutants of human rhodopsin associated with severe forms of Autosomal Dominant Retinitis Pigmentosa (ADRP)." (PMID 19214218, 2009). "Indeed, CRISPR/Cas9 constructs were also successfully delivered by electroporation in photoreceptor cells to target and disrupt by NHEJ the rhodopsin mutated allele in heterozygous P23H mice and in S334ter rats, both model of autosomal dominant retinitis pigmentosa." (PMID 31551698, 2019). "Chronic ER stress has been implicated in a wide range of diseases, including autosomal dominant retinitis pigmentosa (ADRP), which is characterized by age-dependent retinal degeneration caused by mutant rhodopsin alleles." (PMID 37464094, 2023). "The most common mutation in RP is the rhodopsin gene (RHO) mutation, which directly results in photoreceptor degeneration and contributes to 25% of autosomal dominant retinitis pigmentosa (ADRP)." (PMID 37709773, 2023). "RHO (Rhodopsin) gene was responsible for about 25% of all cases of autosomal dominant retinitis pigmentosa (ADRP)." (PMID 36312652, 2022). "When mice and rats express mutant rhodopsin, they experience photoreceptor cell death and, much as humans, develop the clinical signs of autosomal dominant retinitis pigmentosa (ADRP)." (PMID 29354133, 2017). "Using this approach we found that certain rhodopsin point mutants in TM1 and TM5 that are associated with autosomal dominant retinitis pigmentosa, reconstitute into vesicles as monomers but retain wild-type (WT)-like scramblase activity." (PMID 29196630, 2017). "Consistent with our results, recent reports also indicate a role for AP-2 in the apoptosis mediated by visual arrestin binding to a rhodopsin mutant found in certain humans diagnosed with autosomal dominant retinitis pigmentosa." (PMID 26788723, 2016). "There are at least five genes, RHO, NRL, NR2E3, CRX, and RP1, associated with both autosomal dominant retinitis pigmentosa (ADRP) and autosomal recessive retinitis pigmentosa (ARRP)." (PMID 25692141, 2015). "We previously reported activation of the unfolded protein response (UPR) in P23H rhodopsin (RHO) retinas with autosomal dominant retinitis pigmentosa (ADRP)." (PMID 24378535, 2014). "In 1993, Naash and colleagues generated a transgenic mouse with three point mutations in rhodopsin (V20G, P23H, and P27L; termed VPP) that resembles the P23H mutation found in many humans with autosomal dominant retinitis pigmentosa." (PMID 20806040, 2010).